TMEM183A (transmembrane protein 183A)
Synonyms: C1orf37
Tractability: Antibody: UniProt predicts a signal peptide or a membrane-spanning region; the Human Protein Atlas places it where antibodies can reach. PROTAC: ubiquitination databases record sites on it.
Gene: Protein-coding gene on chromosome 1 (203,007,356 to 203,024,848, forward strand). Ensembl gene ENSG00000163444.
Subcellular location: Membrane
Subcellular location (Human Protein Atlas): Plasma membrane; Cell Junctions; Nucleoplasm
Gene Ontology:
Molecular function: protein binding
Cellular component: SCF ubiquitin ligase complex; membrane
Genetic constraint (gnomAD): Loss-of-function variants: 19 observed, 41.54 expected, observed/expected ratio (o/e) 0.46, 90% interval 0.32 to 0.67. The upper end of that interval is the gene's LOEUF score, 0.67, which puts it in group 2 of 6, group 1 being the genes least tolerant of losing a copy. Missense variants: 324 observed, 450.5 expected, observed/expected ratio (o/e) 0.72, 90% interval 0.66 to 0.79. Synonymous variants: 159 observed, 163.8 expected, observed/expected ratio (o/e) 0.97, 90% interval 0.85 to 1.11.
Homologues: Orthologues: chimpanzee TMEM183A (100% identical), macaque TMEM183A (100% identical), dog TMEM183A (97% identical), pig TMEM183A (97% identical), guinea pig TMEM183A (97% identical), rat Tmem183a (95% identical), mouse Tmem183a (93% identical), rabbit TMEM183A (90% identical), zebrafish tmem183a (65% identical), tropical clawed frog tmem183a (63% identical), Drosophila melanogaster fsd (21% identical).
Diseases named in the same sentence as TMEM183A in open-access papers:
TMEM183A is named in the same sentence as 3 diseases in open-access papers, as found by Europe PMC text mining. Sharing a sentence is not in itself a finding about the gene and the disease. The quoted sentences say what the papers report.
hearing loss (1 paper, 2022). "Using a functional C-start assay to pre-screen for phenotypes prior to AM1-43 staining validation, we identified one new gene (tmem183a) associated with hearing loss." (PMID 35202345, 2022). "To identify whether disease-associated candidate genes could be screened by the multiplexed mutation strategy, we selected two genes associated with hearing loss: tmem183a and zgc103499." (PMID 35202345, 2022). "Our results showed that the AM1-43 staining of tmem183a-KO zebrafish was abnormal, consistent with the conclusion that this gene may be associated with hearing loss." (PMID 35202345, 2022).
TMEM183A also shares sentences with these, for which no sentence is quoted: epilepsy (1 paper); hepatocellular carcinoma (1).